IGLV2-14 (immunoglobulin lambda variable 2-14)
Description:
V region of the variable domain of immunoglobulin light chains that participates in the antigen recognition. Immunoglobulins, also known as antibodies, are membrane-bound or secreted glycoproteins produced by B lymphocytes. In the recognition phase of humoral immunity, the membrane-bound immunoglobulins serve as receptors which, upon binding of a specific antigen, trigger the clonal expansion and differentiation of B lymphocytes into immunoglobulins-secreting plasma cells. Secreted immunoglobulins mediate the effector phase of humoral immunity, which results in the elimination of bound antigens. The antigen binding site is formed by the variable domain of one heavy chain, together with that of its associated light chain. Thus, each immunoglobulin has two antigen binding sites with remarkable affinity for a particular antigen. The variable domains are assembled by a process called V-(D)-J rearrangement and can then be subjected to somatic hypermutations which, after exposure to antigen and selection, allow affinity maturation for a particular antigen.
Synonyms: IGLV214; V1-4
Tractability: Antibody: its Gene Ontology location is reachable by antibodies, with high confidence; UniProt places it where antibodies can reach, with medium confidence; UniProt predicts a signal peptide or a membrane-spanning region.
Gene: Immunoglobulin variable (V) gene on chromosome 22 (22,758,700 to 22,759,218, forward strand). Ensembl gene ENSG00000211666.
Subcellular location: Secreted; Cell membrane
Pathways (Reactome):
Immune System: Antigen activates B Cell Receptor (BCR) leading to generation of second messengers; CD22 mediated BCR regulation; Classical antibody-mediated complement activation; FCERI mediated Ca+2 mobilization; FCERI mediated MAPK activation; FCERI mediated NF-kB activation; FCGR activation; Fc epsilon receptor (FCERI) signaling; Immunoregulatory interactions between a Lymphoid and a non-Lymphoid cell; Initial triggering of complement; Regulation of Complement cascade; Regulation of actin dynamics for phagocytic cup formation; Role of LAT2/NTAL/LAB on calcium mobilization; Role of phospholipids in phagocytosis
Disease: FCGR3A-mediated IL10 synthesis; FCGR3A-mediated phagocytosis; Potential therapeutics for SARS
Hemostasis: Cell surface interactions at the vascular wall
Vesicle-mediated transport: Scavenging of heme from plasma
Gene Ontology:
Molecular function: antigen binding
Biological process: immune response
Cellular component: extracellular exosome; extracellular region; immunoglobulin complex; plasma membrane
Homologues: Paralogues in human: IGLV2-18 (90% identical), IGLV2-11 (89% identical), IGLV2-23 (88% identical), IGLV2-8 (88% identical), IGLV1-40 (72% identical), IGLV2-33 (71% identical), IGLV1-50 (68% identical), IGLV1-44 (63% identical), IGLV1-36 (62% identical), IGLV1-47 (62% identical), IGLV6-57 (62% identical), IGLV1-51 (61% identical), and 81 more.